SIRPA (signal regulatory protein alpha)
Description:
Immunoglobulin-like cell surface receptor for CD47. Acts as docking protein and induces translocation of PTPN6, PTPN11 and other binding partners from the cytosol to the plasma membrane. Supports adhesion of cerebellar neurons, neurite outgrowth and glial cell attachment. May play a key role in intracellular signaling during synaptogenesis and in synaptic function (By similarity). Involved in the negative regulation of receptor tyrosine kinase-coupled cellular responses induced by cell adhesion, growth factors or insulin. Mediates negative regulation of phagocytosis, mast cell activation and dendritic cell activation. CD47 binding prevents maturation of immature dendritic cells and inhibits cytokine production by mature dendritic cells. Plays a role in antiviral immunity and limits new world arenavirus infection by decreasing virus internalization (By similarity). Receptor for THBS1. Interaction with THBS1 stimulates phosphorylation of SIRPA (By similarity). In response to THBS1, involved in ROS signaling in non-phagocytic cells, stimulating NADPH oxidase-derived ROS production.
Synonyms: SHPS-1; Bit; Sirp-alpha-1; CD172a; MFR; MYD1; PTPNS1; SHPS1; SIRP; MYD-1; P84; SIRPalpha; SIRPalpha2
Tractability: Antibody: its Gene Ontology location is reachable by antibodies, with high confidence; UniProt predicts a signal peptide or a membrane-spanning region. PROTAC: ubiquitination databases record sites on it; its protein half-life has been measured.
Gene: Protein-coding gene on chromosome 20 (1,892,726 to 1,940,592, forward strand). Ensembl gene ENSG00000198053.
Subcellular location: Membrane
Pathways (Reactome):
Cell-Cell communication: Signal regulatory protein family interactions
Hemostasis: Cell surface interactions at the vascular wall
Immune System: Neutrophil degranulation
Gene Ontology:
Molecular function: cell-cell adhesion mediator activity; protein antigen binding; protein binding; GTPase regulator activity; protein binding involved in heterotypic cell-cell adhesion; protein phosphatase binding; protein phosphatase inhibitor activity; protein tyrosine kinase binding
Biological process: cellular response to interleukin-12; negative regulation of inflammatory response; positive regulation of reactive oxygen species metabolic process; regulation of gene expression; regulation of tumor necrosis factor production; regulation of type II interferon production; cell adhesion; cell migration; cellular response to hydrogen peroxide; cellular response to interleukin-1; cellular response to type II interferon; monocyte extravasation; negative regulation of canonical NF-kappaB signal transduction; negative regulation of chemokine (C-C motif) ligand 5 production; negative regulation of cytokine production involved in inflammatory response; negative regulation of ERK1 and ERK2 cascade; negative regulation of interferon-beta production; negative regulation of interleukin-6 production; negative regulation of JNK cascade; negative regulation of lipopolysaccharide-mediated signaling pathway; negative regulation of macrophage inflammatory protein 1 alpha production; negative regulation of nitric oxide biosynthetic process; negative regulation of phagocytosis; negative regulation of tumor necrosis factor production; positive regulation of phagocytosis; and 6 more
Cellular component: cell surface; extracellular exosome; plasma membrane; ficolin-1-rich granule membrane; membrane; tertiary granule membrane
Genetic constraint (gnomAD): Loss-of-function variants: 7 observed, 42.37 expected, observed/expected ratio (o/e) 0.17, 90% interval 0.093 to 0.31. The upper end of that interval is the gene's LOEUF score, 0.31, which puts it in group 1 of 6, group 1 being the genes least tolerant of losing a copy. Missense variants: 464 observed, 639.75 expected, observed/expected ratio (o/e) 0.73, 90% interval 0.67 to 0.78. Synonymous variants: 264 observed, 268.87 expected, observed/expected ratio (o/e) 0.98, 90% interval 0.89 to 1.09.
Homologues: Orthologues: chimpanzee SIRPA (99% identical), dog SIRPA (78% identical), mouse Sirpa (66% identical), rat Sirpa (62% identical), mouse Sirpb1b (43% identical), mouse Sirpb1a (43% identical), mouse Sirpb1c (43% identical), mouse Gm5150 (20% identical), rat LOC100909964 (18% identical), mouse Sirpd (15% identical), rat AABR07008876.1 (15% identical). Paralogues in human: SIRPB1 (61% identical), SIRPG (56% identical), SIRPD (16% identical), SIRPB2 (15% identical).
Diseases named in the same sentence as SIRPA in open-access papers:
SIRPA is named in the same sentence as 224 diseases in open-access papers, as found by Europe PMC text mining. Sharing a sentence is not in itself a finding about the gene and the disease. The quoted sentences say what the papers report.
melanoma (41 papers, 2013 to 2025). A malignant, usually aggressive tumor composed of atypical, neoplastic melanocytes. "Further survival analysis indicated that high levels of SPP1 + SIRPα + macrophages were associated with a favorable prognosis in melanoma patients treated with immunotherapy." (PMID 39696410, 2024). "Additionally, CD47 expression in cancer cells, such as melanoma and colon cancer, has been linked to immune evasion mechanisms mediated by SIRPα signaling." (PMID 39160226, 2024). "Furthermore, mice harboring inactivating mutations at the SIRPα cytoplasmic tail show similar growth and metastasis of implanted syngeneic melanoma tumor cells as wild-type mice, suggesting again that disruption of CD47-SIRPα alone does not yield an effective antitumor response." (PMID 29387053, 2017). "Melanoma-expressed CD47 interacts with SIRPα on macrophages, protecting the melanoma cells from phagocytosis." (PMID 40082557, 2025). "By contrast, in other VISTA and SIRPα studies expression was related to poor prognosis, and VISTA expression was linked to anti-PD-1 resistance in melanoma." (PMID 40897819, 2025). "When the whole cluster was considered - glioma and glioblastoma with their close HC neighbors melanoma and renal cell carcinoma, elevated SIRPA became a statistically significant feature." (PMID 40788962, 2025). "Studies have shown that cytotoxic T-cells exert stronger anti-melanoma effects on cells overexpressing SIRPα, and the addition of anti-PD-L1 antibodies significantly enhances this killing effect." (PMID 40589735, 2025). "As observed in melanoma, blockade of SIRPα supported a significant slowing of tumor growth in both tumor models." (PMID 38577107, 2024). "The discrepancy between colon cancer and melanoma is fascinating and raises several key questions about the role of SIRPα in different tumor contexts and the potential contribution it makes at different stages of tumor evolution." (PMID 38577107, 2024). "The effects of SIRPα blockade were not limited to melanoma and translated to other solid tumors, namely pancreatic and breast tumors showing a conserved anti-phagocytic pathway activated in suppressive myeloid cells across multiple tumor types." (PMID 38577107, 2024). "Inhibiting SIRPα in melanoma cells hinders tumor eradication by activated CD8+ T cells within a coculture setup." (PMID 38342925, 2024). "Herein, we fabricated a hybrid cell membrane nanovesicle with PD-1 and SIRPα co-decoration for combination immunotherapy in melanoma." (PMID 39588148, 2024). "The modulation of the CD47/SIRPα axis and phagocytosis by HDAC6is was investigated using murine and human melanoma cell lines and macrophages." (PMID 38414061, 2024). "In a melanoma mouse model, PD-1/SIRPα NVs significantly suppressed 77% of tumor growth and elicited a robust antitumor immune response for immunotherapy." (PMID 39588148, 2024). "It has also been reported that inhibition of CD47 or SIRPα with antagonistic antibodies enhances the phagocytic activity of TAMs and suppresses tumor growth in preclinical models of glioblastoma, melanoma, lymphoma, and breast and colorectal cancer." (PMID 34573091, 2021). "The CD47-SIRPα interaction appears to activate and direct the migration of SIRPα+ cells including neutrophils, melanoma cells and monocytes." (PMID 34093583, 2021). "Increased endocytosis of CD47KO melanoma cells by CD11c+SIRPα+ DCs is assumed to be a mechanism for enhanced activation of these DCs following vaccination with CD47KO tumor cells." (PMID 31996683, 2020). "In fact, the use of a murine Ab anti-SIRPα reduced tumorigenesis in mice inoculated with cells from renal cell carcinoma or melanoma." (PMID 31921125, 2019). "In contrast, antibody triggering of SIRPα in melanoma cells led to a decreased phosphorylation of SIRPα and a decreased interaction with SHP-2." (PMID 23776650, 2013).
melanoma (continued). "Additionally, Z. Zhou and his research team uncovered a unique function of SIRPα in melanoma cells: as a marker for melanoma cells, the expression level of SIRPα diminishes progressively as melanoma progresses." (PMID 40589735, 2025). "This suggests that endogenous SIRPα in melanoma cells plays a positive role in PD-1/PD-L1-induced T-cell-mediated anticancer immunity, while the absence of SIRPα may lead to increased resistance to PD-L1 therapy." (PMID 40589735, 2025). "For instance, melanoma cells with low SIRPα expression exhibit suppressed CD8+ T-cell cytotoxicity." (PMID 40589735, 2025). "Following anti-SIRPα treatment of B16.F10.GFP tumor-bearing mice (melanoma cells overexpressing GFP), we detected a significant increase in the frequency of moDCs, M-MDSCs, and cDC2s sampling tumor-derived material as determined by detection of tumor-derived GFP signal within the cells." (PMID 38577107, 2024). "Furthermore, the internalization of PD-1/SIRPα NVs was examined in B16F10 melanoma cells using CLSM analysis." (PMID 39588148, 2024). "Consequently, in mice bearing melanoma xenografts, PD-1/SIRPα nanovesicles substantially promoted the infiltration of CD8+ T cells and the polarization of M1-type tumor-associated macrophages (TAMs), collectively enhancing therapeutic outcomes." (PMID 39588148, 2024). "Mice harboring SIRPα-deficient melanoma tumors exhibit no response to anti-PD-L1 treatment, underscoring the significant impact of melanoma-specific SIRPα overexpression on immunotherapy response." (PMID 38342925, 2024). "Therefore, the novelty of the present study relies on the use of HDAC6i to control the CD47/SIRPα axis by modulating their expression in melanoma cells and macrophages, respectively." (PMID 38414061, 2024). "recently showed that mice bearing SIRPα-deficient melanomas had no response to anti-PD-L1 treatment, but SIRPα overexpression significantly enhanced immunotherapy response." (PMID 38577107, 2024). "Therefore, after assessing the modulatory role of HDAC6 on macrophage phenotype, we evaluated the effects of HDAC6 inhibition in modulating the CD47/SIRPα axis in melanoma cells and macrophages." (PMID 38414061, 2024). "Indeed, we showed that, even in an aggressive melanoma tumor model, SIRPα blockade dampened the inhibitory signal which contributed to the myeloid cells suppressive state and induced higher T CD8+:Treg ratio within the TME." (PMID 38577107, 2024). "In addition, anti-mouse SIRPα (P84 or MY-1) Ab treatment markedly inhibits the growth of tumors formed by SIRPα-expressing renal cell carcinoma and melanoma in mice." (PMID 33763066, 2021). "An increased attraction of SHP-2 to the phosphorylated SIRPα in resting melanoma cells, resulted in an increased cell migration compared to stimulated melanoma cells that displayed a decreased phosphorylation of SIRPα and thereby a decreased attraction of SHP-2." (PMID 23776650, 2013). "Studies in other cell types, including kidney podocytes and melanoma cells, suggested that SIRPα maintains tyrosine phosphorylation in the cytoplasmic domain and association with SHP-(1/2); cell surface CD47 ligation, on the other hand, triggers SIRPα dephosphorylation and releases SHP proteins." (PMID 24143245, 2013). "Notably, the absence of SIRPα expression signifies melanoma dedifferentiation, a critical phenotype associated with immunotherapy efficacy." (PMID 38342925, 2024). "Altogether, our results suggest that HDAC6 controls SIRPα expression in macrophages and melanoma patients and that HDAC6i can be used to downregulate the expression of anti-phagocytic signals and upregulate pro-phagocytic signals, which may enhance the phagocytic capacity of macrophages." (PMID 38414061, 2024). "Investigating the blockade of CD47 in the B16-F10 melanoma model showed there was decreased CD47 expression relative to NDV alone presumably due to anti-CD47 and SIRPα-Fc binding of tumoral CD47 and receptor internalization or blockade of SIRPα binding." (PMID 41322194, 2025).
melanoma (continued). "Lastly, we evaluated the antitumor properties of the combination of NextA and anti-SIRPα and NextA and anti-CD47 in vivo using the SM1 melanoma mouse model." (PMID 38414061, 2024). "Lastly, to evaluate the antitumor activity of Nexturastat A in combination with anti-CD47 or anti-SIRPα antibodies, we performed in vivo studies using the SM1 and/or B16F10 melanoma mouse models." (PMID 38414061, 2024). "As shown in this study, HDAC6 inhibition enhances phagocytosis of SM1 melanoma cells, an event regulated by the CD47/SIRPα axis." (PMID 38414061, 2024). "Mice bearing B16F10 melanoma xenografts were established and subjected to treatment with PBS, Blank NVs, PD-1 NVs, SIRPα NVs, and PD-1/SIRPα NVs for five administrations." (PMID 39588148, 2024). "Our hybrid nanovesicles (PD-1/SIRPα NVs) demonstrated high specificity to PD-L1 and CD47 ligands, facilitating the phagocytosis of melanoma cells by macrophages." (PMID 39588148, 2024). "We inoculated SM1 melanoma cells in C57BL/6 mice (n = 11–19 mice per group) and treated with NextA or anti-SIRPα following the experimental outline in Supp." (PMID 38414061, 2024). "In this context, a recently reported dual inhibitor of CD47/SIRPα and TIGIT/PVR pathways merits further study for utility as an ICI in melanoma." (PMID 36768931, 2023). "For melanoma, breast cancer, and NSCLC, blocking the CD47/SIRPα pathway is an effective treatment strategy." (PMID 37138855, 2023). "Disrupting CD47/SIRPα signaling transduction by blocking antibodies (Hu5F9-G4 and CC-90002) could increase macrophage phagocytosis of multiple tumor cells and has been proved as a promising immunotherapeutic method for melanoma, breast cancer, small cell lung cancer and acute myeloid leukemia." (PMID 31829270, 2019). "It significantly inhibited the growth of SIRPα-expressing renal cell carcinoma and melanoma cells, but not of non-SIRPα-expressing cells." (PMID 40589735, 2025). "Single-cell proteomics confirmed that elevated SIRPα expression originated from melanoma cells rather than macrophages and enhanced T cell-mediated tumor killing." (PMID 40356928, 2025). "Furthermore, combining CSPG4-targeting CAR-Ms with strategies inhibiting CD47/SIRPα “don’t eat me” signaling synergistically enhanced CAR-M-mediated phagocytosis and robustly inhibited melanoma spheroid growth in 3D." (PMID 40082557, 2025). "Therefore, our studies support the rationale for combining HDACis and anti-CD47 to treat melanoma, as this combination targets both the receptor and the ligand of the CD47/SIRPα axis." (PMID 38414061, 2024). "Furthermore, HDAC6is such as Nexturastat A (NextA) downregulate SIRPα on macrophages and modulate CD47 expression in melanoma cells." (PMID 38414061, 2024). "In summary, our study represents a novel approach to target the CD47/SIRPα axis by controlling the expression of “do not eat me” signals on melanoma cells and macrophages." (PMID 38414061, 2024). "In addition, HDAC6 inhibition diminished the expression of SIRPα, increased the expression of other pro-phagocytic signals in macrophages, and downregulated CD47 expression in mouse and human melanoma cells." (PMID 38414061, 2024). "ICB responders had higher SIRPA expression in melanoma cells than non-responders, demonstrating the predictive potential of SIRPA expression in melanoma cells." (PMID 38066642, 2023). "Analysis of 60 immuno-oncology genes in melanoma patients revealed that higher SIRPα expression in tumor cells correlated with better responses to anti-PD-1 therapy and improved patient outcomes, contrasting with its traditional immunosuppressive role in macrophages." (PMID 40356928, 2025). "Overall, our results suggest that the combination of NextA and anti-SIRPα does not provide an additive effect to reduce tumor growth of SM1 melanoma, potentially due to the downregulation of SIRPα on macrophages by NextA, which might decrease the efficacy of anti-SIRPα." (PMID 38414061, 2024).
melanoma (continued). "In a melanoma dataset, we found that patients responding to Pembrolizumab or Nivolumab immunotherapy exhibited a higher signature score for SPP1 + SIRPα + macrophages than non-responders." (PMID 39696410, 2024). "Furthermore, by re-analysis of the public monocytic melanoma dataset GSE120575, we found that patients who did not respond to PD-1/CTLA4 inhibitors had higher SIRPα expression on monocyte/macrophage cells." (PMID 37291116, 2023).